SNAI2 (snail family transcriptional repressor 2)
Diseases named in the same sentence as SNAI2 in open-access papers (continued):
Sharing a sentence is not in itself a finding about the gene and the disease.
lung carcinoma (54 papers, 2010 to 2025). "In gastric and lung cancers, abnormal expression of SNAI2 is associated with poor prognosis." (PMID 35392402, 2022). "Conversely, Dub3 and Pellino have been shown to interact with Snai2 in breast and lung cancer, respectively, stabilizing the protein and promoting cancer cell migration, invasion, and proliferation." (PMID 39062049, 2024). "This research also indicated genes other than TP63 that were co-downregulated with SNAI2 in several online Oncomine Lung Cancer datasets." (PMID 35201505, 2022). "The prototypical EMT inducer TGFβ and its downstream signaling molecule SNAI2 were inversely correlated with EpCAM expression in human lung cancers." (PMID 36077658, 2022). "Previous studies have demonstrated that TCF4 can interact with TWIST1 to promote the expression of EMT-related genes, such as CDH2, VIM, SNAI1, and SNAI2, in embryonic stem and lung cancer cells." (PMID 35406121, 2022). "TGFβ overexpression strongly inhibited the expression of EpCAM in both human and murine lung cancer cells, but stimulated the expression of SNAI2, which could bind to the E-box in epcam promoter to suppress its transcription." (PMID 36077658, 2022). "Furthermore, the strong inverse correlation of SNAI2/SLUG with ESR1 underlines and validates the prognostic relevance of ESR1 in lung cancer." (PMID 25928859, 2015). "Snail family transcriptional repressor 2 (SNAI2), also called SNAIL2 or Slug, is a classical EMT‐related transcriptional inhibitor with an N‐terminal SNAG domain and a C‐terminal DNA‐binding domain, was negatively associated with ERα expression in both BC and lung cancer." (PMID 37881785, 2023). "In addition, this connection could also be observed in clinical specimens, which showed that USP5 was positively correlated with SNAI2 expression in two independent lung cancer datasets." (PMID 37726816, 2023). "Similarly, MARVELD3 silencing decreases CDH1 and increases SNAI2 expression in lung cancer." (PMID 32260415, 2020). "Expression levels of NOTCHs and their target genes (SNAI1, SNAI2, HES2, HEY2) are positively correlated with EMT scores in LUAD, indicating activation of the NOTCH pathway in mesenchymal lung cancer cells." (PMID 40189704, 2025). "When SNAI2 and SOX9 are co-expressed in human lung carcinoma, SNAI2 can protect SOX9 avoid from ubiquitin-mediated proteasomal degradation, which is necessary for SOX9 to promote cancer stem cells and maintain its stem-like phenotype." (PMID 36674577, 2023). "Here, we found that FOXA1 knockdown decreased CDH1 (epithelial marker) but increased CDH2, VIM, SNAI2, and PTHLH (mesenchymal markers) in A549 lung cancer cells." (PMID 35897813, 2022). "As an epithelial marker, CDH1, was decreased and mesenchymal markers, CDH2, VIM, SNAI2, and ITGA5 were increased in PGC1α-silenced epithelial types of A549, H358, and Calu-1 lung cancer cells." (PMID 33917757, 2021). "In lung cancer, SNAI2/SLUG is known as a critical EMT inducer that suppresses CDH1 expression and metastasis." (PMID 27323831, 2016). "It has been reported that SNAI2 promotes the EMT process as well as metastatic phenotypes in several cancers as breast and lung cancer cells." (PMID 27760172, 2016). "The role of KLF10 in suppressing TGF-β-induced EMT was reported in lung cancer, demonstrating that KLF10 functions as a transcriptional repressor, particularly of the EMT-promoting transcription factor SLUG/SNAI2, thereby limiting the ability of TGF-β to induce EMT." (PMID 38279278, 2024). "In addition, ectopic FOXA1 expression significantly reversed TGFβ1-mediated expression of EMT markers, such as CDH1, CDH2, VIM, SNAI2, and PTHLH, in A549 lung cancer cells." (PMID 35897813, 2022). "In addition, macrophage, the major cell type constituting tumor microenvironment, produces TGFβ to modulate EpCAM expression on tumor cells through TGFβ-SNAI2 axis to promote EMT and metastasis in lung cancer." (PMID 36077658, 2022).
lung carcinoma (continued). "To examine whether the induction of EMT reduces HER2 expression, we analyzed mRNA expression of ERBB2, epithelial phenotype markers CDH1, EPCAM, MUC1 and OCLN, mesenchymal phenotype markers CDH2, FN1, SNAI2, and VIM in the A549 cell line (HER2-high human lung cancer epithelial cell line)." (PMID 34575017, 2021). "In our study, we could confirm the negative prognostic effect of SNAI2/SLUG expression in advanced lung cancer, indicating the prognostic effect of EMT." (PMID 25928859, 2015). "In particular, SNAI2/SLUG is also a negative prognostic factor for relapse and overall survival in resectable, early stage lung cancer." (PMID 25928859, 2015). "The data demonstrated, that only SNAI2 mRNA was affected, although differentially in the two cell lines, with a downregulation in the H23 lung carcinoma and upregulation in PANC-1 K-Ras(V12)/Akt2-kd clone A contribution of Akt in Slug/SNAI2 regulation is not without presence in the literature." (PMID 38291468, 2024).
colorectal cancer (42 papers, 2009 to 2025). A primary or metastatic malignant neoplasm that affects the colon or rectum. "displayed that PIK3R3 promoted colorectal cancer metastasis via SNAI2‐induced epithelial‐to‐mesenchymal transition, suggesting a potential target for metastatic colorectal cancer." (PMID 39692250, 2024). "The elevated YAP expression promotes EMT by upregulating the SNAI2 gene (SLUG) expression in colorectal cancer cells." (PMID 38607003, 2024). "SOX13 is induced by hepatocyte growth factor through the JAK2/STAT3 signaling pathway, promoting metastasis in colorectal cancer by upregulating SNAI2 and c-MET expression." (PMID 39726600, 2024). "We demonstrated that SNAI2 is upregulated in colorectal cancers, and correlates with a cancer-stem-like cell phenotype and the expression of specific stem cell markers." (PMID 37239099, 2023). "SOX13 promotes colorectal cancer metastasis by transactivating SNAI2 and c-MET and regulates cancer stem-like properties and tumorigenicity in hepatocellular carcinoma cells." (PMID 35631574, 2022). "Studies have found that SOX13 can promote colorectal cancer metastasis by activating SNAI2 and c-MET." (PMID 34122521, 2021). "These were necessary for the effect of GAPLINC in promoting colorectal cancer cell invasion partly via increasing the expression of snail family zinc finger 2 (SNAI2)." (PMID 27259250, 2016). "Similarly, SNAI2, which encodes for a zinc-finger transcription factor regulating epithelial-mesenchymal transition and is overexpressed in colorectal tumors, was positively regulated by BHLHE40, and SNAI2 is capable of stimulating colorectal cancer cell invasion and tumor formation." (PMID 36890812, 2023). "In human colorectal cancer cells, MALAT1 expression is up-regulated by YAP1, sponges miR-126-5p and miR-20b-5p, and thereby up-regulates the expression of tumor cell stemness proteins such as Oct4 and Nanog and metastasis-associated molecules such as VEGF, SNAI2, and TWIST." (PMID 32174966, 2020). "Analysis of the Cancer Genome Atlas Colorectal Cancer (COADREAD) RNA-Seq data set showed a significant positive relationship between KIT and SNAI2 mRNA expression (n = 380, Pearson r = 0.3704, p < 0.0001)." (PMID 36362141, 2022). "In addition, dictamnine hinders colorectal cancer growth in conjunction with the downregulation of HIF-1α and snail family transcriptional repressor 2 (SNAI2) expression in vivo." (PMID 34575983, 2021). "Previous studies on hepatocellular carcinoma, breast and colorectal cancers showed that sOPN could contribute to the metastasis through enhancing EMT-related transcription factors such as TWIST1, SNAI1 and SNAI2 and then decreasing the adhesion of tumor cells." (PMID 34070192, 2021). "Snail2 (SNAI2), in particular, has been reported to have a key role in the invasion and migration of cancer and we have previously demonstrated it can promote EMT in RAS-active colorectal cancer cells." (PMID 32269211, 2020).
colon carcinoma (41 papers, 2010 to 2024). "For instance, lncSNHG15 promotes cancer progression in colon cancer by preventing Snai2 ubiquitination." (PMID 39062049, 2024). "Supporting this, VDR RNA expression correlates directly with differentiation and inversely with SNAI1 and SNAI2 RNA expression in human colon tumors." (PMID 32854355, 2020). "The results displayed that ZEB2 and SNAI2 were both downregulated in liver metastasis tissues compared with primary colon cancer tissues." (PMID 30530918, 2018). "It was recently demonstrated that SNAI2 is involved in determining the stem cell state of breast and colon cancer." (PMID 29041931, 2017). "The results of our study are relevant for the clinic, as VDR expression is downregulated in approximately two-thirds of advanced colon tumors associated to the upregulation of SNAI1 and SNAI2 genes that code for SNAIL1/SNAIL2 transcriptional repressors." (PMID 21858154, 2011). "In addition, the expressions of ZEB2 and SNAI2 were measured in the same 15 pairs of primary colon cancer tissues and corresponding liver metastasis tissues." (PMID 30530918, 2018). "Similarly, differential expression of some transcription factors involved in epithelial-to-mesenchymal transitions (i.e. ZEB1, SNAI1, and SNAI2) was variably observed in the colon cancer cell lines when exposed to the inflammatory media." (PMID 29462209, 2018). "In addition, the SNAI2 signature score was notably elevated in the CAFs compared with their normal counterparts in the stromal profiles of ovarian, breast, and colon cancer." (PMID 29041931, 2017). "Furthermore, the advantageous expression of SNAI2 in the tumor stroma was next confirmed in another four profiling datasets of ovarian, breast and colon cancer." (PMID 29041931, 2017). "A recent study showed that a histone deacetylase inhibitor, trichostatin A, which induces SNAI1 and SNAI2 expression, inhibits SLC2A5/GLUT5 expression and thereby sensitizes colon cancer cells to cisplatin and oxaliplatin." (PMID 39458997, 2024). "At least in colon cancer, ALDH1A3 increases invasion by upregulating EMT-inducing transcription factor zinc finger E-box binding homeobox 1 (ZEB1) and SNAI2 and by inhibiting MET-promoting miR-200 family microRNAs." (PMID 39251846, 2024). "In colon cancer, ALDH1A3 upregulated transcription factor zinc finger E-box binding homeobox 1 (ZEB1) and snail family transcriptional repressor 2 (SNAI2) by inhibiting miR-200 family members, leading to increased invasion." (PMID 36672441, 2023). "Our data revealed that B3GALT5-AS1 directly binds to the promoter of miR-203, represses miR-203 expression, upregulates miR-203 targets ZEB2 and SNAI2, induces EMT, and finally suppresses colon cancer liver metastasis." (PMID 30530918, 2018). "All these results suggested that B3GALT5-AS1 inhibited miR-203, upregulated ZEB2 and SNAI2, induced EMT, and suppressed colon cancer liver metastasis in vivo." (PMID 30530918, 2018). "Third, we finally analyzed the expression of transcription factors known to be mediators of EMT in colon cancer cells, namely ZEB1, SNAI1 (also known as Snail), SNAI2 (also known as Slug), and TWIST." (PMID 29462209, 2018). "Also, GAPLINC can increase SNAI2 expression by interacting with PSF and NONO, thereby promoting colon cancer invasion." (PMID 36741921, 2023). "We found that the expression of ZEB1, SNAI1 and SNAI2 were clearly induced in the two colon cancer cell lines by MACRO-CM from U937 macrophages, with the exception of HT-29 cells that did not expressed detectable levels of SNAI2 mRNA under any culture condition." (PMID 29462209, 2018).
pancreatic cancer (35 papers, 2012 to 2026). "For example, BMP-4 induces the expression of the EMT-associated transcription factors SNAI1 and SNAI2, which encode Snail and Slug, respectively, in a Smad4-dependent manner in ovarian and pancreatic cancer cells." (PMID 35693928, 2022). "EGR1 acts as a pro-metastatic factor in pancreatic cancer cells, promoting cell migration and invasion through the SNAI2–EMT pathway." (PMID 41048344, 2025). "Taken together, these data indicated that SNAI2 played a crucial role in pancreatic cancer cell proliferation and invasion." (PMID 37251370, 2023). "To reveal the role of SNAI2 in pancreatic cancer cells cell proliferation and invasion, we designed the following assays." (PMID 37251370, 2023). "qRT-PCR and Western blot analysis suggested that SNAI2 was overexpressed in the four pancreatic cancer cell lines (PANC-1, SW1990, BxPC-1, and SW979) when compared with its expression in the control." (PMID 37251370, 2023). "In the present study, we identified EGR1 as a pro-metastasis factor in pancreatic cancer cells, which promoted cell migration and invasion via the SNAI2-EMT pathway." (PMID 36932397, 2023). "Our data confirm that knockdown of BCL9L leads to an up-regulation of E-cadherin expression with concomitant down-regulation of SNAI2 gene expression in pancreatic cancer cells." (PMID 27713160, 2016). "While the role of Snail in pancreatic cancer progression is well established, the role of Slug (Snai2) in pancreatic tumorigenesis is less well understood." (PMID 27364947, 2016). "For instance, EGR1 increased pancreatic cancer’s liver metastasis through the P300/SNAI2 pathway." (PMID 39866235, 2025). "We then used Western blot assay to look at the EMT markers (E-cadherin, N-cadherin, and vimentin) to see if SNAI2 could affect EMT in pancreatic cancer cells." (PMID 37251370, 2023). "Finally, the immunoblot was used to quantify the SNAI2 expression levels, and the proliferative and invasive ability of pancreatic cancer cells was determined by colony formation and transwell assays." (PMID 37251370, 2023). "Finally, the knockdown of SNAI2 significantly weakened the proliferative and invasive ability of pancreatic cancer cells." (PMID 37251370, 2023). "Besides, EGR1 was positively correlated with EMT process in pancreatic cancer, via a SNAI2-dependent pathway." (PMID 36932397, 2023). "The effect of SNAI2 was then tested and verified in pancreatic cancer." (PMID 36932397, 2023). "Thus, we wondered whether p300/CBP was involve in the transcription regulation of EGR1 on the SNAI2 promoter in pancreatic cancer." (PMID 36932397, 2023). "Furthermore, IHC results also revealed that SNAI2 expression was located in the nuclear, SNAI2 protein was expressed to some extent in both normal pancreatic tissue and pancreatic cancer, and the staining level was significantly increased in pancreatic cancer." (PMID 37251370, 2023). "Notch has been shown to regulate pancreatic cancer stem cells and would have a role in the acquisition of epithelial-mesenchymal transition (EMT) by inducing SNAI2 expression due to JAG1 overexpression." (PMID 22925330, 2012). "The comparison of EMT-TFs expression levels between PDAC and healthy pancreatic tissue revealed significantly elevated mRNA levels of SNAI1, SNAI2, ZEB1 and TWIST in pancreatic cancer tissue, while ZEB2 expression was higher in normal pancreatic tissue (p < 0.05)." (PMID 41481650, 2026). "In addition to the regulation of EMT, SNAI2 also conferred resistance to MEK1/2 inhibitors and gemcitabine in pancreatic cancer, as previously reported." (PMID 36932397, 2023). "Interestingly, restoration of the expression of miR-200 downregulates SNAI2 and other inhibitory transcription factors, and reverses EMT in pancreatic cancer cells." (PMID 31749661, 2019). "Interestingly, the proposed squamous subtype of pancreatic cancer exhibits high expression of FOSL1, TGFB2, SNAI2, and FN1, which is consistent with the FRA1:EMT phenotype we describe here." (PMID 27220889, 2016).
pancreatic cancer (continued). "Recently, SNAI2 was shown to promote EMT, invasion and metastasis in a pancreatic cancer cell line." (PMID 22894607, 2012). "Furthermore and in accordance with the literature TGF-β treatment of control Panc-1 cells induced a time-dependent, significant downregulation of E-Cadherin expression and a concomitant induction of mesenchymal gene expression (SNAI2, VIM) in pancreatic cancer cells." (PMID 27713160, 2016).